TXNRD2 (thioredoxin reductase 2)
Description:
Involved in the control of reactive oxygen species levels and the regulation of mitochondrial redox homeostasis. Maintains thioredoxin in a reduced state. May play a role in redox-regulated cell signaling.
Synonyms: SelZ; TRXR2; TR; TR3; TXNR2; GCCD5; TR-BETA
Tractability: Small molecule: a high-quality ligand is known; it belongs to a druggable protein family. PROTAC: ubiquitination databases record sites on it; its protein half-life has been measured; a small molecule that binds it is known.
Target class: Enzyme; Oxidoreductase
Gene: Protein-coding gene on chromosome 22 (19,875,517 to 19,941,820, reverse strand). Ensembl gene ENSG00000184470.
Subcellular location: Mitochondrion
Subcellular location (Human Protein Atlas): Cytosol; Mitochondria
Pathways (Reactome):
Cellular responses to stimuli: Detoxification of Reactive Oxygen Species
Gene Ontology:
Molecular function: protein binding; protein homodimerization activity; thioredoxin-disulfide reductase (NADPH) activity; flavin adenine dinucleotide binding; oxidoreductase activity; oxidoreductase activity, acting on a sulfur group of donors, NAD(P) as acceptor; protein-containing complex binding
Biological process: cell redox homeostasis; response to oxygen radical; cellular oxidant detoxification; response to hyperoxia; response to oxidative stress; response to selenium ion
Cellular component: mitochondrion; cytosol; mitochondrial matrix; axon; dendrite; neuronal cell body
Genetic constraint (gnomAD): Loss-of-function variants: 67 observed, 69.57 expected, observed/expected ratio (o/e) 0.96, 90% interval 0.79 to 1.18. The upper end of that interval is the gene's LOEUF score, 1.18, which puts it in group 5 of 6, group 1 being the genes least tolerant of losing a copy. Missense variants: 644 observed, 697.72 expected, observed/expected ratio (o/e) 0.92, 90% interval 0.86 to 0.99. Synonymous variants: 301 observed, 280.25 expected, observed/expected ratio (o/e) 1.07, 90% interval 0.98 to 1.18.
Homologues: Orthologues: macaque TXNRD2 (98% identical), chimpanzee TXNRD2 (97% identical), guinea pig TXNRD2 (88% identical), mouse Txnrd2 (84% identical), rat Txnrd2 (83% identical), pig TXNRD2 (79% identical), dog TXNRD2 (69% identical), tropical clawed frog txnrd2 (68% identical), zebrafish txnrd2.2 (65% identical), Caenorhabditis elegans trxr-2 (46% identical), zebrafish txnrd2.1 (27% identical). Paralogues in human: TXNRD3 (54% identical), TXNRD1 (54% identical), GSR (37% identical), DLD (28% identical), AIFM3 (19% identical), AIFM1 (19% identical), PYROXD1 (18% identical).
Diseases named in the same sentence as TXNRD2 in open-access papers:
TXNRD2 is named in the same sentence as 70 diseases in open-access papers, as found by Europe PMC text mining. Sharing a sentence is not in itself a finding about the gene and the disease. The quoted sentences say what the papers report.
prostate carcinoma (10 papers, 2012 to 2024). A carcinoma that arises from epithelial cells of the prostate gland. "TXNRD2, thioredoxin reductase 2, a known selenoprotein and DNA damage response gene, is implicated in cancer, such as prostate cancer and colorectal cancer." (PMID 39543761, 2024). "Méplan reviewed several SNP studies of selenoproteins and their relationship with prostate cancer and found that serum selenium and selenoprotein concentrations were related to prostate cancer only when the allele of TXNRD2 rs9605031 was CT/TT." (PMID 37765058, 2023). "For instance, individuals with the AA and AG alleles in the TXNRD2 rs3804047 gene variant have shown an increased risk of prostate cancer with selenium supplementation." (PMID 37765058, 2023). "The observation that SNPs in both TXNRD1 and TXNRD2 genes are affecting prostate cancer risk supports the proposed role of the corresponding proteins in prostate function and/or tumour development." (PMID 23133653, 2012). "There was also evidence of lower risk of advanced prostate cancer in homozygous CC carriers for rs9605030 in the TXNRD2 gene (OR = 0.53, 95% CI = 0.29–0.95, p = 0.03) as serum SePP increased." (PMID 23133653, 2012). "However, thioredoxin reductase 2 protein was clearly shown to be a biomarker of prostate cancer-associated reactive stroma whose presence distinguishes the stroma associated with benign prostatic hyperplasia from that associated with prostate cancer." (PMID 23762225, 2013). "Similar trends were observed for the TXNRD2 rs8141691 variant, where individuals with the AA allele were less likely to develop high-grade prostate cancer risk with selenium supplementation, while those with the GG and AG alleles had an increased risk of high-grade prostate cancer." (PMID 37765058, 2023). "MiR-17-3p elevated ROS levels by inhibiting three primary mitochondrial antioxidants, MnSOD, glutathione peroxidase 2 (Gpx2) and thioredoxin reductase 2 (TrxR2), remarkably strengthening the sensitivity of prostate cancer cells to IR." (PMID 35081965, 2022). "The study extended earlier work by showing consistent significant interactions between serum markers of Se status and TXNRD1, TXNRD2 and SELK genotype with respect to risk of high-grade or advanced stage prostate cancer." (PMID 23133653, 2012). "More relevant to our work, it has been shown that miR-17-3p downregulates important anti-oxidant enzymes, such as manganese superoxide dismutase, glutathione peroxidase-2 and thioredoxin reductase-2 (TrxR2) in prostate cancer cell lines and blood mononuclear cells." (PMID 27505139, 2016). "Moreover, a previous study demonstrated that targeting mitochondrial antioxidants, including manganese superoxide dismutase (MnSOD), glutathione peroxidase 2 (Gpx2), and thioredoxin reductase 2 (TrxR2) by microRNA-17-3p remarkably sensitized prostate cancer cells to IR." (PMID 34249928, 2021). "Xu and colleagues reported miR-17-3p could repress three major mitochondrial antioxidant enzymes (manganese superoxide dismutase (Mn-SOD), glutathione peroxidase 2 (Gpx2), and thioredoxin reductase 2 (TrxR2)) and enhance the radiosensitivity of prostate cancer cells." (PMID 32411322, 2020). "Thus overall, the data from this EPIC-Heidelberg nested case-control study indicate that together Se status and GPX1, SEPP1, TXNRD1, TXNRD2, and SELK genotype significantly alter risk of high-grade or advanced stage prostate cancer in a population with suboptimal Se intake." (PMID 23133653, 2012). "In conclusion, this study shows a significant interaction between serum markers of Se status and TXNRD1, TXNRD2 and SELK genotype with respect to high-grade or advanced stage prostate cancer." (PMID 23133653, 2012). "There were significant interactions between Se status and TXNRD1, TXNRD2 and SELK genotype with respect to high-grade or advanced stage prostate cancer, so emphasising the importance of the combination of Se intake and genotype in determining prostate cancer risk." (PMID 23133653, 2012).
glucocorticoid deficiency (8 papers, 2014 to 2026). "Pertinently, human mutations in thioredoxin reductase 2 have also been shown to result in isolated glucocorticoid deficiency." (PMID 29850793, 2018). "Moreover, genetic variants of NNT and TXNRD2, which are involved in maintaining the mitochondrial ROS balance, have been shown to be disease causing in several patients with familial glucocorticoid deficiency informing the importance of the mitochondrial ROS system for steroidogenesis." (PMID 38885337, 2024). "This study expands the TXNRD2 variant spectrum and highlights the importance of considering FGD5 in patients with isolated glucocorticoid deficiency, particularly those with ECG abnormalities." (PMID 40726908, 2025). "Isolated deficiency of TXNRD2 leads to glucocorticoid deficiency (TXNRD2 [MIM: 617825]) without any reported neurological, thyroid, or muscular symptoms." (PMID 39753114, 2025). "The details of our case are consistent with those in previous cases of the TXNRD2 mutation with only glucocorticoid deficiency and no mineralocorticoid deficiency." (PMID 40726908, 2025). "A homozygous mutation in human TXNRD2 has been shown to cause familial glucocorticoid deficiency without a cardiac phenotype." (PMID 38251125, 2024). "A homozygous mutation in human TXNRD2 results in glucocorticoid deficiency without a cardiac phenotype.Nervous system-specific Txnrd2 knockout mice do not show any neurological abnormalities.Constitutive gene inactivation is embryonic-lethal." (PMID 38251125, 2024). "In contrast to the Txnrd2-knockout mouse model, in which embryonic lethality as a consequence of hematopoietic and cardiac defects is described, absence of TXNRD2 in humans leads to glucocorticoid deficiency." (PMID 24601690, 2014). "The TXNRD2 mutation in this family and the other recently described FGD syndromes due to mutations in NNT and MCM4 highlight important pathogenic pathways in addition to defective ACTH signaling, causing glucocorticoid deficiency." (PMID 24601690, 2014). "Therefore, TXNRD2 and NNT mutations result in glucocorticoid deficiency, but the exact mechanism underlying this relationship is unknown." (PMID 40726908, 2025). "This, together with the higher production of cortisol in comparison with aldosterone, may explain the particular susceptibility of the zona fasciculata to oxidative stress, and hence, individuals with TXNRD2 and NNT mutations primarily develop glucocorticoid deficiency." (PMID 24601690, 2014). "Similarly, our patient 17-3959 with a homozygous truncating variant in TXNRD2 had a syndromic manifestation characterized by low cortisol, intellectual disability, epilepsy, dysmorphic features, truncus arteriosus, and omphalocele, unlike isolated glucocorticoid deficiency that was reported in OMIM." (PMID 30237576, 2019).
Adrenal insufficiency (7 papers, 2014 to 2026). Insufficient production of steroid hormones (primarily cortisol) by the adrenal glands. "First, in several children with familial forms of X-linked AHC (NR0B1/DAX-1), MC2R defects or TXNRD2 disruption, we were able to make a diagnosis of adrenal insufficiency early on in the presentation or whilst the child was presymptomatic." (PMID 34258490, 2021). "A similar number of individuals (4.5%) were found to have adrenal insufficiency due to a homozygous stop gain mutation (p.Y447*) in thioredoxin reductase 2 (TXNRD2)." (PMID 34258490, 2021). "The sensitivity of adrenal glands to oxidative damage, is illustrated by three different rare conditions having in common adrenal insufficiency and oxidative stress: mutations in NNT, TXNRD2, or AAAS." (PMID 34867779, 2021). "Of note, several genes associated with adrenal insufficiency in humans were not differentially expressed during early development; namelyNNT,TXNRD2,AAAS,MCM4 andSGPL1." (PMID 28459107, 2017). "Absence of TXNRD2 is associated with adrenal insufficiency in this consanguineous kindred, with all affected members being homozygous for the identified genetic defect." (PMID 24601690, 2014). "Because heterozygote carriers of the p.Y447X TXNRD2 mutation have normal adrenal function, we would predict that haploinsufficiency of TXNRD2 would not lead to an abnormal adrenal phenotype, and consistent with this, we were unable to identify any published reports of adrenal insufficiency in DGS." (PMID 24601690, 2014).
dilated cardiomyopathy (7 papers, 2014 to 2025). Cardiomyopathy which is characterized by dilation and contractile dysfunction of the left and right ventricles. "Murine models with TXNRD2 deficiency develop fatal dilated cardiomyopathy through mechanisms involving mitochondrial degeneration and impaired contractility." (PMID 40726908, 2025). "Mutations in the human TXNRD2 gene that affect the flavin-adenine dinucleotide binding domain result in a dilated cardiomyopathy." (PMID 34579115, 2021). "TXNRD2 has been associated with two different, unrelated diseases: dilated cardiomyopathy and familial glucocorticoid deficiency." (PMID 34769022, 2021). "As mentioned in the previous section, functional mutations in the human TXNRD2 gene result in a dilated cardiomyopathy." (PMID 34579115, 2021). "Two variants in TXNRD2, p.Ala59Thr and p.Gly375Arg, were identified in patients that suffered from dilated cardiomyopathy." (PMID 34769022, 2021). "In humans, two novel heterozygous mutations in TXNRD2 were identified in 3 of 227 patients with a diagnosis of dilated cardiomyopathy." (PMID 24601690, 2014). "By contrast, Txnrd2 knockout embryos die at 13 days as a result of defects in hematopoiesis and cardiac development, and cardiac-specific Txnrd2 knockout results in a fatal dilated cardiomyopathy with structurally abnormal cardiomyocytes." (PMID 34579115, 2021). "Txnrd2 deletion in mice is embryonically lethal at day 13 as a consequence of a combination of cardiac and hematopoietic defects, with cardiac-specific ablation resulting in a fatal dilated cardiomyopathy." (PMID 24601690, 2014).
glaucoma (7 papers, 2016 to 2024). Increased pressure in the eyeball due to obstruction of the outflow of aqueous humor. "Our data suggest an association between TXNRD2 genepolymorphism (rs35934224) with primary open-angle glaucoma in an admixedBrazilian population." (PMID 34431894, 2021). "Both SOD2 and TXNRD2 are mitochondrial antioxidant stress enzymes, and mitochondrial dysfunction has been causally related to glaucoma." (PMID 28053689, 2016). "Association analysis of rs35934224 in TXNRD2 and rs6478746 in LMX1B with primary open-angle glaucoma." (PMID 34408771, 2021). "Nossos dados sugerem uma associação entre o polimorfismo dogene TXNRD2 (rs35934224) e o glaucoma primário deângulo aberto em uma população brasileira." (PMID 34431894, 2021). "We verified the European glaucoma gene TXNRD2 andidentified a novel candidate locus encompassing EXOC4 that requiresfurther follow up in large African studies." (PMID 30317457, 2018). "Regarding the genetic aspect, SNPs with high OR values for glaucoma exposure on cataract were TMCO1-AS1 (rs2814471 with OR = 1.370), GAS7 (rs12602519 with OR = 1.178), ABCA1;SLC44A1 (rs2472493 with OR = 1.162), and GNB1L;TXNRD2 (rs58714937 with OR = 1.153)." (PMID 38674349, 2024).
breast carcinoma (6 papers, 2008 to 2025). "Udler did not observe a significant association between any of the TXNRD1 or TXNRD2 SNPs and breast cancer survival." (PMID 24278290, 2013). "Another investigation found that wogonin inhibited the production of the protective enzyme TXNRD2 that controls the generation of ROS within cells and slows the progression of breast cancer by activating cellular apoptosis." (PMID 41164269, 2025). "Five SNPs, GPX3 rs2070593 (p=0.002), GPX4 rs2074451 (p=0.046), SELS rs9874 (p=0.029), TXNRD1 rs17202060 (p=0.007) and TXNRD2 rs7322262 (p=0.025), significantly interacted with DOBS to alter breast cancer risk." (PMID 24278290, 2013). "These include apparent decreases in caspase-3 and mmp-9, but increases in cadherin 1, thioredoxin reductase 2, and glutathione peroxidase 3 in the KO mammary carcinomas." (PMID 20932318, 2010). "Of these SNPs, only TXNRD2 rs732262 (padj =0.38) did not remain statistically significantly associated with breast cancer risk after multiple comparison adjustment." (PMID 24278290, 2013). "In mouse and human fibroblasts as well as melanoma, colon, and breast cancer cell lines, the OS-induced expression of KLF9 leads to a further increase in intracellular ROS, as a consequence of KLF9 suppression of Thioredoxin Reductase 2 (TXNRD2; a key anti-oxidant protein) gene expression." (PMID 38067370, 2023).
Parkinson disease (4 papers, 2012 to 2024). A progressive degenerative disorder of the central nervous system characterized by loss of dopamine producing neurons in the substantia nigra and the presence of Lewy bodies in the substantia nigra and locus coeruleus. "GSEA analysis of TXNRD2 showed that Alzheimer disease, Huntington disease, Parkinson disease were related to the high expression group of TXNRD2." (PMID 33154194, 2020).
selenium deficiency (4 papers, 2020 to 2022). A nutritional deficiency disease resulting from inadequate selenium levels in the body, which can lead to impaired function of selenoproteins essential for antioxidant defense and thyroid hormone metabolism. "Consistently with other studies, the expressions of TXNRD2 and TXNRD3 were the highest in the selenium deficiency group." (PMID 35663374, 2022).
22q11.2 deletion syndrome (3 papers, 2016 to 2020). 22q11.2 deletion syndrome (DS) is a chromosomal anomaly which causes a congenital malformation disorder whose common features include cardiac defects, palatal anomalies, facial dysmorphism, developmental delay and immune deficiency. "A microdeletion in humans containing TBX1 and surrounding genes, including TXNRD2, has been linked to DiGeorge syndrome (22q11.2 deletion syndrome), the most common microdeletion disorder in humans." (PMID 31821332, 2019). "A homologous region is deleted in most cases of DiGeorge syndrome, and haplo-insufficiency of TXNRD2 has been considered for contributing to the phenotype for DiGeorge syndrome." (PMID 31821332, 2019). "Among them, CRKL, TBX1, TXNRD2, GP1BB were known to be involved in DiGeorge syndrome." (PMID 26742958, 2016).
Ataxia (3 papers, 2008 to 2019). Ataxia refers to impaired coordination of voluntary muscle movement. "Furthermore, nervous system-specific knockout of Txnrd1 in mice leads to smaller body size with ataxia and tremor while mice deficient in Txnrd2 develop normally." (PMID 27656880, 2016). "While NS-specific Txnrd2 null mice develop normally, mice lacking Txnrd1 in the NS were significantly smaller and displayed ataxia and tremor." (PMID 18350150, 2008). "A study using mice with nervous system specific (NS-specific) deletion of TXNRD1 and TXNRD2 demonstrated while NS-specific TXNRD2 null mice develop normally, mice lacking TXNRD1 in the NS are significantly smaller and display ataxia and tremor." (PMID 30677045, 2019).
cardiomyopathy (3 papers, 2014 to 2025). A disease of the heart muscle or myocardium proper. "TXNRD2 mutations demonstrate tissue-selective pathogenicity, primarily targeting adrenal fasciculata while sparing other high-energy organs—a stark contrast to systemic mitochondrial disorders caused by TXNRD2 defects (e.g., cardiomyopathy in encephalopathic forms)." (PMID 40726908, 2025). "Interestingly, neither the heterozygote nor homozygote individual, with absence of TXNRD2, showed any evidence of cardiomyopathy or conduction disease." (PMID 24601690, 2014).
schizophrenia (3 papers, 2016 to 2022). A major psychotic disorder characterized by abnormalities in the perception or expression of reality. "Circumstantial evidence has also suggested that altered function of the mitochondrial selenoprotein thioredoxin reductase 2 (TrxR2) may contribute to schizophrenia." (PMID 35204134, 2022).
Alzheimer disease (2 papers, 2015 to 2020). A progressive, neurodegenerative disease characterized by loss of function and death of nerve cells in several areas of the brain leading to loss of cognitive function such as memory and language. "For example, MRPL40 knockouts in the fruit fly show defects in neurogenesis that compromise neurodevelopment, and knockdowns of TXNRD2 in worms overexpressing human beta-amyloid peptide as a model for Alzheimer’s disease were more susceptible to muscular dysfunction and paralysis." (PMID 26137170, 2015).
cognitive deficits (2 papers, 2024 to 2026). "In 22q model transgenic mice, mitochondrial TXNRD2 has been shown to impact synaptic function and is associated with long-range cortical connectivity and psychosis-related cognitive deficits." (PMID 39259737, 2024).